TULP1 (TUB like protein 1)
Description:
Required for normal development of photoreceptor synapses. Required for normal photoreceptor function and for long-term survival of photoreceptor cells. Interacts with cytoskeleton proteins and may play a role in protein transport in photoreceptor cells (By similarity). Binds lipids, especially phosphatidylinositol 3-phosphate, phosphatidylinositol 4-phosphate, phosphatidylinositol 5-phosphate, phosphatidylinositol 3,4-bisphosphate, phosphatidylinositol 4,5-bisphosphate, phosphatidylinositol 3,4,5-bisphosphate, phosphatidylserine and phosphatidic acid (in vitro). Contribute to stimulation of phagocytosis of apoptotic retinal pigment epithelium (RPE) cells and macrophages.
Synonyms: TUBL1; LCA15; RP14
Tractability: Small molecule: a structure with a bound ligand is known; it has a high-quality binding pocket. Antibody: UniProt places it where antibodies can reach, with high confidence; its Gene Ontology location is reachable by antibodies, with high confidence. PROTAC: ubiquitination databases record sites on it.
Gene: Protein-coding gene on chromosome 6 (35,497,874 to 35,512,896, reverse strand). Ensembl gene ENSG00000112041.
Subcellular location: Cytoplasm; Cell membrane; Secreted; Synapse
Gene Ontology:
Molecular function: actin filament binding; phosphatidylinositol-4,5-bisphosphate binding; protein binding
Biological process: detection of light stimulus involved in visual perception; positive regulation of phagocytosis; retina homeostasis; dendrite development; eye photoreceptor cell development; photoreceptor cell maintenance; protein localization to cilium; visual perception
Cellular component: cell projection; plasma membrane; cilium; photoreceptor inner segment; photoreceptor outer segment; synapse; cytoplasm; extracellular region
Genetic constraint (gnomAD): Loss-of-function variants: 50 observed, 62.1 expected, observed/expected ratio (o/e) 0.81, 90% interval 0.64 to 1.02. The upper end of that interval is the gene's LOEUF score, 1.02, which puts it in group 4 of 6, group 1 being the genes least tolerant of losing a copy. Missense variants: 746 observed, 717.15 expected, observed/expected ratio (o/e) 1.04, 90% interval 0.98 to 1.11. Synonymous variants: 297 observed, 286.14 expected, observed/expected ratio (o/e) 1.04, 90% interval 0.94 to 1.14.
Gene-disease validity (ClinGen):
ClinGen rates the evidence that TULP1 causes each of these diseases.
Leber congenital amaurosis 15 (autosomal recessive): Definitive.
Homologues: Orthologues: chimpanzee TULP1 (99% identical), macaque TULP1 (98% identical), dog TULP1 (86% identical), mouse Tulp1 (80% identical), rat Tulp1 (79% identical), pig TULP1 (79% identical), rabbit TULP1 (76% identical), guinea pig TULP1 (70% identical), zebrafish tulp1b (45% identical), zebrafish tulp1a (45% identical), zebrafish TULP1 (38% identical), tropical clawed frog tulp2 (38% identical), and 2 more. Paralogues in human: TUB (44% identical), TULP3 (36% identical), TULP2 (31% identical), TULP4 (19% identical), WDR35 (12% identical).
Diseases named in the same sentence as TULP1 in open-access papers:
TULP1 is named in the same sentence as 38 diseases in open-access papers, as found by Europe PMC text mining. Sharing a sentence is not in itself a finding about the gene and the disease. The quoted sentences say what the papers report.
retinal degeneration (18 papers, 2008 to 2025). Degeneration of the retina. "Our studies show the complexity of antibody-mediated autoimmunity in developing the possible pathogenic mechanism responsible for retinal degeneration in TULP1 autoimmunity." (PMID 40141211, 2025). "In conclusion, we described a patient with biallelic TULP1 variants, displaying an atypical perivascular pattern of retinal degeneration." (PMID 38450199, 2024). "Biallelic pathogenic variants in TULP1 are mostly associated with severe rod-driven inherited retinal degeneration." (PMID 36769033, 2023). "Revealing the function of TULP1 is crucial for understanding the pathogenesis of TULP1-associated retinal degeneration." (PMID 36396940, 2022). "Deletion of Tulp1 in mice causes severe retinal degeneration and deficient protein transport in the photoreceptors." (PMID 36396940, 2022). "Mutations in TUB-like protein 1 (TULP1) are associated with severe early-onset retinal degeneration in humans." (PMID 36396940, 2022). "The course of retinal degeneration in Tulp1−/− mice is similar to that found in TULP1-linked human IRD patients." (PMID 32973439, 2020). "Loss of dTULP and TULP1 in Drosophila rhabdomeric and mammalian ciliary photoreceptors, respectively, leads to progressive retinal degeneration." (PMID 31259686, 2019). "Mutation of Tulp1, a member of the TULPs, in human and mice, exhibits retinal degeneration due to the mislocalization of rhodopsin." (PMID 24068974, 2013). "Tubby is linked to adult onset obesity and retinal degeneration in mice and the Tubby like proteins (TULP1-4) are also implicated or directly involved in cilia related processes." (PMID 23604077, 2013). "This relatively small number suggests that TULP1 mutations are a rare cause for early-onset retinal degeneration." (PMID 18432314, 2008). "A haplotype of three polymorphic marker alleles (D6S1583, D6S1611, D6S291) linked to TULP1 on chromosome 6p21.31, co-segregated with retinal degeneration in this family." (PMID 18432314, 2008). "These AAbs could be generated when TULP1 is released from damaged photoreceptor cells, leading to the production of AAbs, and then those AAbs could be implicated in secondary retinal degeneration." (PMID 40141211, 2025). "TULP1 mutations could lead to a syndromic disorder, as evidenced by a recessive mutation in the Tubby gene in mice, which was associated not only with retinal degeneration but also with obesity, cochlear abnormalities, and diabetes." (PMID 38785568, 2024). "Therefore, our data suggest that the pathological mechanism underlying the onset of retinal degeneration is a TULP1 folding defect, a conclusion that is supported by experimental results." (PMID 36769033, 2023). "In addition, mutations in another TULPs family member, TULP1 (also known as RP14), is known to cause retinal degeneration in both humans and mice." (PMID 36650547, 2023). "TULP1 was first reported as a pathogenic gene of retinal degeneration in 1998." (PMID 36396940, 2022). "Loss of TULP1 results in severe early-onset retinal degeneration." (PMID 36396940, 2022). "However some of these mouse models [e.g. Tulp1 ko, CSPα ko] manifest a rapid retinal degeneration with a substantial loss of photoreceptor cells that is accompanied by severe functional defects before one month of age." (PMID 22912773, 2012). "Mutations of TULP1 cause retinal degeneration in both humans and mice." (PMID 18432314, 2008). "In mouse models, genetic ablation of TULP1 resulted in retinal degeneration, with marked deterioration of the photoreceptor layer, and, in effect, apoptosis of both rods and cones." (PMID 40141211, 2025). "Comparative histology was undertaken in Tulp1-/-, rhodopsin-/- (Rho-/-) and retinal degeneration slow-/- (Rds-/-) mouse retinas." (PMID 32655363, 2020).
retinal degeneration (continued). "Using various cellular markers, we evaluated the architecture of Tulp1-/- retinas compared to retinas from Rho-/- and retinal degeneration slow (Rds-/-) mice, where retinal degeneration is believed to originate from photoreceptors." (PMID 32655363, 2020). "Anti-TULP1 AAbs uniquely label the retina and may be generated in response to widespread retinal degenerations, including retinal atrophy, vessel attenuation, and RPE changes." (PMID 40141211, 2025). "Tubby-like protein 1 (TULP1) is located approximately 60 kb downstream from FKBP5 and has been reported to be important for vesicular trafficking of photoreceptor proteins and associated with early-onset retinal degeneration." (PMID 37274192, 2023). "Currently, the function of TULP1 and the exact etiology of how TULP1 mutations cause early-onset retinal degeneration have not been clearly established." (PMID 36396940, 2022). "We also considered, whether TULP1 may be expressed in the early post-natal retina of mice, which may contribute to the severe retinal degeneration observed in Tulp1-/- mice." (PMID 32655363, 2020). "Importantly, our Tulp1 and Rpe65 mutant models exhibit a similar time course of retinal degeneration as Mfrprd6 and show similar OS shortening and disorganization at P14 without a change in ONL thickness." (PMID 25357075, 2014). "In addition, the ganglion cell layer was immunostained by anti-TULP1 and anti-Rab6 antibodies, indicating that these proteins could be released at the same time during retinal degeneration and stimulate immune responses." (PMID 40141211, 2025). "This complexity may explain the severe phenotype of TULP1-induced retinal degeneration." (PMID 34360830, 2021). "Overall, in spite of molecular restoration of Tulp1 in a significant proportion of photoreceptor cells, only minimal and transient benefit was found in treated Tulp1−/− retinas and retinal degeneration was not halted." (PMID 32973439, 2020).
retinitis pigmentosa (14 papers, 2008 to 2025). Retinitis pigmentosa (RP) is an inherited retinal dystrophy leading to progressive loss of the photoreceptors and retinal pigment epithelium and resulting in blindness usually after several decades. "The authors suggested that such AAbs blocked the function of the TULP1 protein in the photoreceptor cell in a manner similar to that of the mutated TULP1 gene observed in retinitis pigmentosa (RP)." (PMID 40141211, 2025). "TULP1, also known as Leber congenital amaurosis 15 (LCA15) or retinitis pigmentosa-14 (RP14), has been associated with autosomal recessive early-onset retinal degeneration." (PMID 36396940, 2022). "Mutations in TULP1 result in progressive photoreceptor degeneration in mice and retinitis pigmentosa in humans." (PMID 33187986, 2021). "Mutations in human TULP1 have been associated with early-onset, severe retinitis pigmentosa (RP) and Leber congenital amaurosis (LCA)." (PMID 34360830, 2021). "Dysregulation of TULPs has been implicated in a number of human diseases including retinitis pigmentosa (TULP1 and TULP2), PKD (TULP3), and several cancers (TULP3)." (PMID 33187986, 2021). "Mutations in the gene TULP1 have been associated with two forms of IRDs, early-onset retinitis pigmentosa (RP) and Leber congenital amaurosis (LCA)." (PMID 26987071, 2016). "Retina and anterior neural fold homeobox 2 (RAX2), TUB like protein 1 (TULP1) and G protein subunit gamma transducin 2 (GNGT2) are associated with photoreceptor cells, with TULP1 being involved in retinitis pigmentosa and RAX2 playing a role in the malignant progression of glioblastoma." (PMID 39695086, 2024). "Both Tub and Tulp1 are expressed in the retina, and TULP1 mutations cause retinitis pigmentosa." (PMID 32252387, 2020). "The first mutations in TULP1 genes were discovered in inherited retinal diseases with the gene assigned to human chromosomal region 6p21·3, close to the RP14 locus responsible for an autosomal recessive form of retinitis pigmentosa." (PMID 40141211, 2025). "Homozygosity mapping, combined with candidate-gene analysis, successfully identified genetic defects in TULP1 in two large Pakistani families with early-onset retinitis pigmentosa." (PMID 22665969, 2012). "Interestingly, amino acid substitutions of this conserved arginine within the Tubby domain in the related gene TULP1 have also been identified in retinitis pigmentosa patients." (PMID 36276950, 2022). "Mutations in tubby like protein 1 gene (TULP1) are causative of rare, early onset, severe forms of autosomal recessive retinal degeneration, usually diagnosed as Leber congenital amaurosis 15 (LCA15) or retinitis pigmentosa 14 (RP14) (RetNet - Retinal Information Network, 2019)." (PMID 32655363, 2020).
Leber congenital amaurosis (10 papers, 2008 to 2023). Leber congenital amaurosis (LCA) is a retinal dystrophy defined by blindness and responses to electrophysiological stimulation (Ganzfeld electroretinogram (ERG)) below threshold, associated with severe visual impairment within the first year of life. "More recently, a duplication of two amino acids (FA531–532dup) in exon 15 of Tulp1 was determined to cause an aggressive form of IRD: Leber congenital amaurosis (LCA), or, early-onset retinal degeneration (EORD), in an Algerian family." (PMID 36982165, 2023). "This homozygous region harbored TULP1, a gene known to be mutated in patients with Leber congenital amaurosis (LCA) and arRP." (PMID 22665969, 2012). "To date, 22 distinct pathogenic mutations of TULP1 have been reported in patients with early-onset RP or Leber congenital amaurosis." (PMID 18432314, 2008). "Mutations in the TULP1 gene have been shown to be the underlying cause of early-onset autosomal recessive retinitis pigmentosa (MIM #600132, RP14) and Leber congenital amaurosis (MIM#613843, LCA15)." (PMID 26987071, 2016).
Retinal dystrophy (10 papers, 2012 to 2025). Retinal dystrophy is an abnormality of the retina associated with a hereditary process. "Our research describes the clinical and molecular characteristics of a patient manifesting an atypical retinal dystrophy pattern, marked by the identification of both a previously unreported and a rarely encountered TULP1 variant." (PMID 38450199, 2024). "This study highlights the importance of further clinical and molecular characterization of TULP1 variants to elucidate genotype–phenotype correlations in the context of inherited retinal dystrophies." (PMID 38450199, 2024). "This TULP1 variant was identified through WES in 168 Korean patients with hereditary retinal degeneration." (PMID 38785568, 2024). "In contrast to known forms of retinal dystrophy, including those caused by mutations in the tubby-like protein TULP-1, loss of function of TUB in the proband and two affected family members was associated with early-onset obesity, consistent with an additional role for TUB in energy homeostasis." (PMID 24375934, 2014). "This research established a connection between biallelic TULP1 variants and a wide range of clinical phenotypes, emphasizing the remarkable heterogeneity in TULP1-related retinal dystrophy." (PMID 38450199, 2024). "Various diseases, including RP, Stargardt’s disease, TULP1-related retinal dystrophy, and achromatopsia have been reported." (PMID 35205402, 2022). "In addition, the reported variants were of clinical significance as the PDE6C variant was detected novel, whereas TULP1, MERTK, and MYO7A variants were detected rare and first time found segregating with retinal dystrophies in Pakistani consanguineous families." (PMID 37165311, 2023). "The TULP1 mutation of Asn349Lys is located in the conserved tub domain extending between residues 298 and 536 of TULP1 (AAB53700.1) and is associated with a phenotype of early-onset retinal dystrophy with onset at one and eight years for two patients in the family." (PMID 22605927, 2012). "Notably, it has been suggested that patients carrying homozygous or compound heterozygous TULP1 pathogenic variants, particularly those affecting the tubby domain and/or resulting in a loss-of-function (LOF) effect, typically exhibit a severe, early-onset form of retinal dystrophy." (PMID 38450199, 2024).
night blindness (5 papers, 2008 to 2024). Inability to see clearly in dim light. "Patients harboring TULP1 mutations report early-onset night blindness, and severe visual acuity loss involving both rod and cone photoreceptors." (PMID 34360830, 2021). "Symptoms of night blindness were reported by 11 individuals, including CRB1 or TULP1 mutations (all individuals; three each group), RPGRIP1 or RPE65 mutations (two individuals each) and RDH12 mutations (one individual)." (PMID 29178642, 2017).
cone dystrophy (4 papers, 2023 to 2025). An inherited ocular disorder characterized by the loss of cone cells, the photoreceptors responsible for both central and color vision. "Since then, TULP1 biallelic variants have been extensively associated with various forms of IRDs, including non-syndromic RP, Leber congenital amaurosis, cone dystrophy, and rod–cone dystrophy." (PMID 38450199, 2024). "Although, cone dystrophy associated PDE6C variant independently segregated from RP associated TULP1 variant in family 3, however, nystagmus and complete blindness at the age of 20 years were observed in family members who carried both PDE6C and TULP1 variants." (PMID 37165311, 2023). "However, mild features of RP were observed in some individuals of the same family who were detected homozygous for only TULP1 variant alleles and cone dystrophy was observed in an individual who was carrying only PDE6C variant alleles in homozygous state." (PMID 37165311, 2023). "Of those, thirty-seven had been diagnosed with LCA, eleven with eoRP, six with RP, two were diagnosed with cone dystrophy, and five with “TULP1-RD”." (PMID 36769033, 2023).
Nystagmus (4 papers, 2008 to 2024). Rhythmic, involuntary oscillations of one or both eyes related to abnormality in fixation, conjugate gaze, or vestibular mechanisms. "Contrary to reports in the literature in which nystagmus was a feature of patients with TULP1 mutations, no nystagmus was present in our patients." (PMID 22605927, 2012).
myopia (3 papers, 2017 to 2024). "An individual with RPGRIP1 mutations reported hypermetropia and one TULP1‐affected individual reported myopia." (PMID 29178642, 2017).
retinal diseases (3 papers, 2016 to 2025). "Pathogenic variants of the TULP1 gene discovered in inhered retinal diseases (IRD) exhibit a broad range of severity and clinical presentations." (PMID 40141211, 2025). "No current therapies exist for TULP1-associated retinal disease as the pathologic mechanism of photoreceptor degeneration, linking genotype to phenotype, is currently unknown." (PMID 26987071, 2016).
autoimmune retinopathies (2 papers, 2025). "The detection of anti-TULP1 AAbs in patients with breast cancer suggests that anti-TULP1 AAbs have the potential to be a biomarker for cancer-associated autoimmune retinopathy." (PMID 40567613, 2025). "Nevertheless, the strong association of detectable anti-TULP1 AAbs in breast cancer patients with vision problems indicates its potential as a biomarker for cancer-associated autoimmune retinopathy." (PMID 40141211, 2025). "In autoimmune retinopathy, anti-TULP1 AAbs disrupt protein translocation to the outer segments and are involved in photoreceptor degeneration in a manner similar to the degeneration induced by mutations in the TULP1 gene." (PMID 40567613, 2025). "Despite this, detectable anti-TULP1 AAbs may serve as a biomarker for cancer-autoimmune retinopathy in breast cancer and may also be useful for breast cancer diagnosis." (PMID 40141211, 2025). "Tubby-like protein 1 (TULP1) is a somewhat relatively unknown antigen in autoimmune retinopathies." (PMID 40141211, 2025).
Blindness (2 papers, 2012 to 2023). Blindness is the condition of lacking visual perception defined as a profound reduction in visual perception. "TULP1 mutations were previously reported to cause LCA, a congenital form of severe vision impairment or blindness and early-onset RP." (PMID 22665969, 2012).